IL1B (interleukin 1 beta)
Diseases named in the same sentence as IL1B in open-access papers (continued):
Sharing a sentence is not in itself a finding about the gene and the disease.
endometriosis (continued). "The effects of inflammation on markers of ESC aging were assessed using an established IL-1β treatment protocol that mimics aspects of ESC senescence and endometriosis." (PMID 38879630, 2024). "In endometriosis, the NF-κB pathway becomes activated, leading to the expression of pro-inflammatory genes and the production of cytokines such as TNF-α and IL-1β." (PMID 39229427, 2024). "Higher levels of cytokines or chemokines have also been described in patients with endometriosis, including macrophage migration inhibitory factor, TNF-α, IL-1β, IL-6 and IL-8." (PMID 39595086, 2024). "Elevated levels of pro-inflammatory cytokines, such as interleukin-6 (IL-6), interleukin-1beta (IL-1β), tumor necrosis factor-alpha (TNF-α), and prostaglandin E2 (PGE2) have been consistently identified in women diagnosed with endometriosis." (PMID 39257907, 2024). "NGF is a critical mediator of pain in endometriosis, often upregulated by inflammatory cytokines such as tumor necrosis factor-α (TNF-α) and interleukin-1β (IL-1β)." (PMID 39324359, 2024). "The downregulation of miR-138 expression enhances inflammation in endometriosis by elevating levels of TNF-α, IL-1β, IL-6, and IL-18 through the activation of the NF-κB signaling pathway and VEGF." (PMID 39001478, 2024). "MiR-196a may contribute to progesterone resistance in endometriosis and miR-144-3p has been shown to correlate with cell survival status in human endometriotic lesions and is involved in the regulation of inflammatory mediators such as IL-6, IL-1β, TNFα, PTGS2 and COX2." (PMID 39457531, 2024). "Some studies have shown that endometriosis is a manifestation of pelvic inflammatory disease, with abundant inflammatory factors in the pathologic examination of endometriosis, such as IL-6, macrophage migration inhibitory factor, TNF-α, IL-1b, IL-6, and IL-8." (PMID 39536051, 2024). "Specifically, the levels of TNFα, IL1β, and IL6 are increased in pelvic MΦ isolated from endometriosis patients." (PMID 38559689, 2024). "Recently, we indicated that ASX significantly decreased serum levels of IL‐1β, IL‐6, and TNF‐α in endometriosis patients." (PMID 39479675, 2024). "In this study, we describe twelve patients undergoing surgery for endometriosis with additional immunohistochemical testing for NGF, IL-1β, and nerve bundle density using PGP9.5." (PMID 38785989, 2024). "Cytokine activity, such as proinflammatory cytokines (IL-1β, IL-6) and tumor growth factor-beta (TNF-β), plays an important role in evading immune surveillance and predicting the disease severity of endometriosis." (PMID 36660246, 2023). "Nuclear factor (NF)-κB, a major regulator of inflammatory response, is activated by various cytokines increased in the peritoneal fluid of women with endometriosis, such as TNF-α and IL-1β." (PMID 37108154, 2023). "IL-1β also regulates COX-2 expression; indeed, the ectopic endometriosis cells are more sensitive to the cytokine stimulation in terms of COX-2 expression with respect to normal cells." (PMID 37447296, 2023). "In the case of endometriosis, the peritoneum shows an increased number of activated macrophages (with increased activity) and high levels of many cytokines, such as MMIF, TNFα, IL-1β, IL-6 (largest proportion), and IL-8." (PMID 36979957, 2023). "In that regard, increased levels of IL-1β and TNF-α were found in animals subjected to endometriosis and treated with the vehicle compared to the sham." (PMID 36982152, 2023). "In response to multiple factors such as IL-1β, TNF-α, and TLR4, endometriotic cells activate the NF-κB signaling pathway, affecting endometriosis initiation and progression." (PMID 36769226, 2023). "The expression of IL-6, TNFα, and IL-1β, as markers of inflammation, and TGFβ, as a marker of fibrosis, could be useful tools to predict the response of an individual’s immune system to the different progestins suitable for the treatment of menopausal inflammatory disorders, including endometriosis." (PMID 37298830, 2023).
endometriosis (continued). "These cells are thought to play a significant role in the pathogenesis of endometriosis: TNF-α and IL-1β stimulate ectopic endometrial cells to synthesize histamine-releasing factor (HRF), which is also involved in the pathogenesis of allergy." (PMID 37760889, 2023). "The elevated concentrations of crucial pro-inflammatory cytokines, namely IL-1β, IL-6 and TNF-α, have been demonstrated in patients with endometriosis." (PMID 37143676, 2023). "Several cytokines including IL-1β and TNF-α were reported to be increased in the PF of women with endometriosis." (PMID 36982152, 2023). "The reduction of IL-1β and TNF is conducive to the downregulation of chronic inflammatory processes, which is helpful in the treatment of endometriosis." (PMID 37138868, 2023). "There are other components of innate immunity, including TNF-α, IL-1β, IL-6, IL-17A, ICAM-1/LFA-1, and HMGB-1, that participate in the pathogenesis of endometriosis." (PMID 36865552, 2023). "The levels of IL-1β, one of the pro-inflammatory cytokines secreted upon TLR activation, are significantly higher in the extrauterine tissues and peritoneal fluid of endometriosis patients than that of healthy women." (PMID 37033937, 2023). "IL-1β stimulates COX-2 expression via the mitogen-activated protein kinase (MAPK) signaling pathway, further enhancing the inflammatory response in endometriosis." (PMID 37834449, 2023). "Among the top genes in the two key subnetworks, VEGFA, CXCL8, CCL2, IL1B and PTGS2 were also considered to be highly related to endometriosis in MalaCards." (PMID 35130311, 2022). "qRT–PCR data confirmed that the mRNA levels of interleukin 1-α (IL1A) and interleukin 1-β (IL1B) were increased significantly in GSK591-treated decidualized hEnSCs, which was also observed in the endometrium of endometriosis patients." (PMID 36195592, 2022). "Peritoneal fluid of patients with endometriosis found prostaglandins, levels of activated macrophages, tumor necrosis factor (TNF) ±, IL-1β, and increased proteases." (PMID 36268444, 2022). "Several molecular mechanisms have been pointed out for endometriosis, including inhibiting TNF-α-induced cellular apoptosis and enhancing NALP-3-induced IL-1β production." (PMID 36354688, 2022). "Further, increased levels of TNF-α, IL-1β, IL-6, and IFN-γ have been detected in the serum, peritoneal fluid, and endometrium of women with endometriosis." (PMID 35409294, 2022). "Studies have shown the promise of using IL-1β and TNF-α for the prediction of endometriosis, with specificities of 0.85 and 0.72, respectively." (PMID 36555618, 2022). "The markers related to the pathogenesis of endometriosis in ESCs were evaluated using estradiol, tumor necrosis factor alpha (TNF-α), interleukin 1β (IL-1β), and IL-32, administered alone or in combination with DNG." (PMID 36428561, 2022). "The COX-2 gene is more sensitive to IL-1β stimulation in ectopic endometriotic stromal cells than in eutopic stromal cells and the COX-2/PGE2 pathway is closely related to endometriosis." (PMID 36359004, 2022). "The trends of increased levels of IL-16, IL-18, IL-1β and IFNγ were seen both in PM and PBMC in endometriosis patients." (PMID 35565370, 2022). "Higher levels of expressed IL-6 were also measured in the peritoneal fluid and serum from women with endometriosis, along with TGF-β isoforms, IL-1β, IL-10, and IL-17AF." (PMID 33435569, 2021). "Nevertheless, contradictory results for levels of IL-10, IL-1β, IL-2 and TNF-α in the peritoneal fluid of women with endometriosis has been also reported." (PMID 34639133, 2021). "In addition, IL-1β at certain levels induces ovulation and inhibits endometrial metaplasia, which may be detrimental to embryo implantation and pregnancy maintenance in normal women and women with endometriosis, ultimately leading to infertility." (PMID 33906696, 2021).
endometriosis (continued). "On the other hand, it has been reported that the serum levels of IL-8, MCP-1, IL-10, IL-1β and TGF-β are also increased in patients with endometriosis." (PMID 34639133, 2021). "In the current study’s in vivo experiment, the levels of TNF-α, IL-1β of serum and VEGF of endometriosis lesions significantly decreased in the FC groups at doses of 10, 50, and 150 mg/kg compared with the E2 group." (PMID 33266505, 2020). "Treatment was also associated with a decline in mRNA expression of several pro‐inflammatory cytokines including IL‐6, TNF‐α, IL‐1β and TGF‐β, known to be highly expressed in endometriosis." (PMID 31904910, 2020). "Oxidative stress offers a plausible mechanism to link inflammation and infertility as IL-1β and TNF-α are able to activate apoptotic mechanisms and oocytes from women with endometriosis have exhibited increased rates of apoptosis in the cumulus cells." (PMID 27740937, 2017). "Increasing levels of IL-1β and TNF-α would induce the production of IL-6 by peritoneal mesothelial cells, which would further contribute to the local inflammation observed in endometriosis." (PMID 26247027, 2015). "Their further study showed that cultured peritoneal macrophages from endometriosis patients secreted more AIF-1 than those from unaffected women, and AIF-1 release can be stimulated by IL-1β and IFN-γ." (PMID 24759987, 2014). "In the peritoneal cavity activated macrophages are the major source of IL-1β, IL-6, IL-8 and TNF-α and altered expression of these proinflammatory cytokines has been described in the peritoneal fluid of women with endometriosis." (PMID 24587003, 2014). "Using a surgically induced endometriosis model, we first showed that treatment with LXA4 reduced the volume of endometriotic lesions in part by attenuating pro-inflammatory (IL-1β and IL-6) and pro-angiogenic (VEGF) mediators in endometriotic lesions and PFCs." (PMID 24587003, 2014). "Peritoneal macrophages are known to express inflammatory cytokines, such as IL-6, IL-1β and tumor necrosis factor alpha (TNF-α) and to be increased in number and more activated in patients with endometriosis." (PMID 24039864, 2013). "Based on our data and the existing literature, IL-1β, IL-6, and IL-8 do not appear to be reliable predictive serum biomarkers for endometriosis, as they show high interindividual variability." (PMID 40724945, 2025). "Platelets and other inhibitory cytokines, IL-6, IL-16, IL-17, IL-1β, IL-10, and TGF-β, are found in the peritoneal fluid in patients with endometriosis and function to prevent the NK cells from degranulation and producing interferon (IFN)-γ, impairing the NK cell function." (PMID 40747182, 2025). "For IL-1β, we noted higher levels of IL-1β among the endometriosis cases with moderate dyspareunia as opposed to severe dyspareunia (OR: 5.40; 95% CI: 1.35–21.6)." (PMID 40508188, 2025). "They found that IL-1β and IL-18 levels were elevated in the follicular fluid in the endometriosis group, compared to the non-endometriosis group." (PMID 39769450, 2024). "The increase in IL-1β and TNF-α could stimulate peritoneal mesothelial cells to produce IL-6, thereby exacerbating the local inflammation observed in endometriosis." (PMID 38928175, 2024). "Although no changes in cell uptake were detected, sEVs from endometriosis induced a polarization of macrophages toward an M2 phenotype, characterized by lower IL1B and TNF expression and a tendency to increase MRC1 and ARG1 levels." (PMID 39062452, 2024). "They found elevated levels of pro-inflammatory markers, including TNF-α, IL-6, and IL-1β, in the control group rather than in those with endometriosis." (PMID 39767772, 2024). "Immunolocalization for nerve bundle density around endometriosis using protein gene product 9.5 (PGP9.5), as well as NGF and IL-1β histoscores in endometriosis epithelium/stroma, was performed to evaluate differences in scores between lesions and anatomic subtypes per patient." (PMID 38785989, 2024).
endometriosis (continued). "Treatment with control sEVs did not alter these changes, whereas endometriosis sEVs reduced IL1B expression and did not generate significant changes in MRC1." (PMID 39062452, 2024). "Levels of IL-1β were found to be elevated in fluid collected from endometrioma-affected ovaries compared to that in ovarian fluid from women without endometriosis." (PMID 38732021, 2024). "Moreover, a previously published study identified important proangiogenic factor such as vascular endothelial growth factor (VEGF), IL-1β, IL-6 and IL-8 as well as TNF-α played important roles in the vascularization process in endometriosis." (PMID 37033937, 2023). "Notably, inhibition of miR-138 expression promotes inflammation by increasing levels of TNF-α, IL-1β, IL-6, and IL-18 through activation of the NF-κB signaling pathway and VEGF in endometriosis." (PMID 37834449, 2023). "High levels of malondialdehyde (MDA), pro-inflammatory cytokines (IL-6, TNF-α, and IL-1β), angiogenic factors (IL-8 and VEGF), monocyte chemoattractant protein-1 (MCP-1), and oxidized LDL (ox-LDL) were detected in the peritoneal fluid of endometriosis patients." (PMID 36835217, 2023). "NLRP3/IL-1β contributed to the etiology of endometriosis, and NLRP3 suppressors (MCC950) possibly helped to reduce ovarian endometriosis as well as enhanced the functionality of ovaries affected by endometriosis." (PMID 37033937, 2023). "constructed the co-culture systems of NK cells, macrophages, and ESCs from patients with endometriosis and discovered that the expression of CD16, NKG2D, perforin, and IFN-γ was significantly downregulated, while the secretion of IL-1β, IL-10, and TGF-β was increased." (PMID 36865552, 2023). "Furthermore, factors modulating its secretion (localized hypoxia, IL-1β, TGF-β, EGF and PGE2) are increased in the case of endometriosis." (PMID 36979957, 2023). "In fact, the present study revealed that vaginal mucosa and endometriotic cells responded to increased levels of IL-6, IL-8, IL-1β, and TNF-α when challenged by Candida albicans or by LPS, and these cells present a pivotal role in the inflammatory process in endometriosis and leiomyoma." (PMID 35164046, 2022). "So, the release of several cytokines related to inflammation, including IL-1β, Cox-2, NF-κb, HIF-1α, TNF-α, IL-6, and IL-8, could modulate proliferation and vascularization followed by endometriosis development." (PMID 35059465, 2022). "Of note, the cytokines inhibited by MiodesinTM, such as IL-8, IL-6, IL-1β, and TNF-α are thought to have a key role in the inflammatory process in endometriosis, becoming an interesting tool as an adjuvant for therapeutic schemes in the treatment of endometriosis." (PMID 35164046, 2022). "Serum concentrations of IL-1β, IL-6, hs-CRP, IgG, YKL 40 and PRL, in comparison to the well-known CA 125 levels, were studied with the aim of identifying an additional noninvasive inflammatory marker or set of markers characteristic for endometriosis." (PMID 33669013, 2021). "Interleukin-1β (IL-1β) induced WEE1 expression in endometrial stromal cells (ESCs), suggesting that WEE1 may be upregulated during the endometriosis-induced inflammatory response." (PMID 34686198, 2021). "Therefore, in this study, we decided to examine whether selected parameters of inflammation (IL-1β, IL-6, hs-CRP, IgG, YKL 40 and PRL) could become a set of additional diagnostic markers (all of them or some of them) supporting the diagnosis of advanced endometriosis." (PMID 33669013, 2021). "Peritoneal macrophages from patients with endometriosis display increased activation of the pro-inflammatory transcription factor NF-κB and enhanced protein expression of pro-inflammatory cytokines such as TNF-α, IL-6, IL-1β, and TGF-β." (PMID 32145751, 2020). "Previous studies have showed that IL-1β, IL-6, and TNF-α are increased in women with endometriosis." (PMID 32151056, 2020). "Specifically, increased endometrial TNF, IL-1β, and CCL17 expression are observed in endometriosis." (PMID 36304708, 2020).
endometriosis (continued). "In addition, FC inhibited inflammation by regulating the levels of VEGF IL-1β and TNF-α and suppressed EMT in endometriosis mice." (PMID 33266505, 2020). "IL-37 synthesis is enhanced by IL-1β, TNF-α, IFN-γ, and TGF-β in endometriosis." (PMID 32145751, 2020). "Similarly, IL-1β, IL-6, TNF-α, and prostaglandin E2 (PGE2) were found to be rich in the peritoneal fluid of women with endometriosis." (PMID 31636643, 2019). "The concentrations of IL-1β, IL-1 converting enzyme, IL-8, and regulated on activation, normal T-cell expressed and secreted (RANTES) were increased in the peritoneal fluid of patients with endometriosis." (PMID 31636643, 2019). "For example, levels of pro-inflammatory cytokines IL-1β, IL-6, IL-8, IFN-γ, and TNF-α are elevated in peritoneal fluid and serum of patients with endometriosis and could be used as non-invasive markers of the disease." (PMID 32063886, 2019). "Diverse factors, including TGF-β, TNF-α, IL-1β and IL-6 that have been shown to upregulate ICAM-1 expression in other contexts, are known to increase endometrial cell adhesion to the peritoneum in an in vitro model of endometriosis." (PMID 29772648, 2018). "One study determined that the follicular fluid of naturally matured follicles (without gonadotropin stimulation) in endometriosis patients had higher IL-1β and IL-6." (PMID 30104541, 2018). "As observed when LXA4 was administered on D−1, IL-1β, COX-2, VEGF, MRP4, TGF-β1, TGF-β2, CYP19a1, ERα, GREB1 and c-Myc expression were significantly attenuated whereas MMP-9 and TGF-β3 were upregulated in endometriotic lesions in established endometriosis." (PMID 24587003, 2014). "Clinical observations also indicate that inflammatory mediators, such as cyclooxygenase-2 (COX-2), interleukin-1 beta (IL-1β), interleukin-8 (IL-8), tumor necrosis factor alpha (TNF-α), and prostaglandin E2 (PGE2), are significantly elevated in the peritoneal fluid of patients with endometriosis." (PMID 40004233, 2025). "However, the eQTL results should be interpreted with caution as IL1A and IL1B are known to have highly context‐specific effects, and their roles in endometriosis development and symptomatology are not yet completely defined." (PMID 40938538, 2025). "Notably, the eutopic endometrium of women with endometriosis exhibits elevated levels of inflammatory cytokines, including IL-1β, TNF-α, and IL-8 compared to the control, suggesting that this pro-inflammatory environment contributes to impaired decidualization in endometriosis." (PMID 40072055, 2025). "However, rosiglitazone did not modify the changes in macrophage phenotype induced by endometriosis sEVs, with no significant changes in IL1B or MRC1 expression being observed." (PMID 39062452, 2024). "Among the cytokines, IL-1β may be responsible for the increased proliferation of endometriosis cells, while it does not affect healthy endometrial cells." (PMID 37447296, 2023). "Our results show that several mRNAs and pathways related to immune function, such as IL-1B, CXCR4, IL-7R, STAT4, CD14, and CCR5, as well as the FoxO signaling pathway, the Jak-STAT signaling pathway, and the NF-kappa B signaling pathway, have significant correlations with endometriosis." (PMID 38203209, 2023). "Moreover, TNFα and IL-1β activate the NK-κB signaling pathway, which in turn controls the expression of cytokines and chemokines such as IL-1, IL-6, IL-8, TNF-α, as well as ICAM-1 able to boost inflammation and COX-2 expression in endometriosis implants." (PMID 37447296, 2023). "Hence, in this study, we explored this hypothesis by evaluating a group of key senescence markers, namely p16Ink4, IL-1β, lamin b1, and the SASP, in tissues of women with deep endometriosis." (PMID 35269619, 2022). "Similarly, we found that there was an increase in IL-1β mRNA levels in patients with endometriosis compared to those without endometriosis during the menstrual and luteal phases." (PMID 36555618, 2022).